RN7SL322P (RNA, 7SL, cytoplasmic 322, pseudogene)
Gene: Miscellaneous RNA gene on chromosome 19 (47,581,023 to 47,581,321, forward strand). Ensembl gene ENSG00000276588.
Homologues: Orthologues: chimpanzee Metazoa_SRP (99% identical), macaque Metazoa_SRP (93% identical). Paralogues in human: RN7SL1 (85% identical), RN7SL2 (84% identical), RN7SL3 (84% identical), RN7SL45P (83% identical), RN7SL296P (82% identical), RN7SL732P (82% identical), Metazoa_SRP (81% identical), RN7SL336P (81% identical), RN7SL444P (81% identical), RN7SL769P (81% identical), RN7SL218P (81% identical), RN7SL44P (81% identical), and 704 more.